IL34 (interleukin 34)
Description:
Cytokine that promotes the proliferation, survival and differentiation of monocytes and macrophages. Promotes the release of pro-inflammatory chemokines, and thereby plays an important role in innate immunity and in inflammatory processes. Plays an important role in the regulation of osteoclast proliferation and differentiation, and in the regulation of bone resorption. Signaling via CSF1R and its downstream effectors stimulates phosphorylation of MAPK1/ERK2 AND MAPK3/ERK1.
Synonyms: IL-34; C16orf77; MGC34647
Tractability: Antibody: UniProt places it where antibodies can reach, with high confidence; its Gene Ontology location is reachable by antibodies, with high confidence; UniProt predicts a signal peptide or a membrane-spanning region.
Gene: Protein-coding gene on chromosome 16 (70,579,878 to 70,661,556, forward strand). Ensembl gene ENSG00000157368.
Subcellular location: Secreted
Pathways (Reactome):
Immune System: Other interleukin signaling; Signaling by CSF1 (M-CSF) in myeloid cells
Gene Ontology:
Molecular function: macrophage colony-stimulating factor receptor binding; protein binding
Biological process: interleukin-34-mediated signaling pathway; positive regulation of cell population proliferation; positive regulation of macrophage chemotaxis; positive regulation of macrophage differentiation; positive regulation of macrophage proliferation; positive regulation of MAPK cascade; positive regulation of monocyte differentiation; positive regulation of protein phosphorylation; macrophage colony-stimulating factor signaling pathway; monocyte differentiation; positive regulation of oligodendrocyte differentiation; microglial cell proliferation; positive regulation of cell development; positive regulation of gene expression; positive regulation of multicellular organismal process; regulation of multicellular organismal development
Cellular component: extracellular region; receptor complex
Genetic constraint (gnomAD): Loss-of-function variants: 17 observed, 19.45 expected, observed/expected ratio (o/e) 0.87, 90% interval 0.6 to 1.31. The upper end of that interval is the gene's LOEUF score, 1.31, which puts it in group 5 of 6, group 1 being the genes least tolerant of losing a copy. Missense variants: 332 observed, 277.71 expected, observed/expected ratio (o/e) 1.2, 90% interval 1.09 to 1.31. Synonymous variants: 155 observed, 129.62 expected, observed/expected ratio (o/e) 1.2, 90% interval 1.05 to 1.37.
Homologues: Orthologues: chimpanzee IL34 (99% identical), macaque IL34 (90% identical), dog IL34 (74% identical), pig IL34 (74% identical), rabbit IL34 (70% identical), guinea pig IL34 (68% identical), rat Il34 (68% identical), mouse Il34 (67% identical).
Diseases named in the same sentence as IL34 in open-access papers:
IL34 is named in the same sentence as 202 diseases in open-access papers, as found by Europe PMC text mining. Sharing a sentence is not in itself a finding about the gene and the disease. The quoted sentences say what the papers report.
rheumatoid arthritis (38 papers, 2012 to 2025). A chronic, systemic autoimmune disorder characterized by inflammation in the synovial membranes and articular surfaces. "Elevated levels of IL-34 have been associated with the severity of rheumatoid arthritis and poor prognosis." (PMID 40176879, 2025). "The second ligand of CSF1R, IL-34, is a recently discovered inflammatory cytokine, has associations with various rheumatic conditions such as rheumatoid arthritis, systemic lupus erythematosus, and SS." (PMID 40809841, 2025). "When it comes to autoimmune diseases, IL-34 is associated with rheumatoid arthritis, Sjogren's syndrome and lupus nephritis." (PMID 38230243, 2024). "In patients with rheumatoid arthritis, the synovium expresses IL-34, and high levels of IL-34 in synovial fluid (SF) and serum are associated with synovitis disease progression and severity." (PMID 37551285, 2022). "Of particular interest IL-34 is elevated and implicated in the inflammation process of several inflammatory diseases including rheumatoid arthritis, inflammatory bowel disease, and Sjogren’s syndrome." (PMID 32735214, 2020). "IL-34 has been reported overexpressed in rheumatoid arthritis and involved in RA-associated osteoclastogenesis." (PMID 23409120, 2013). "Serum IL-34 levels are associated with increased disease severity in rheumatoid arthritis." (PMID 40724937, 2025). "Previous studies have revealed that IL-34 is expressed in synovium, and the increased IL-34 levels in serum and synovial fluid (SF) are associated with synovitis severity and disease progression in rheumatoid arthritis (RA) patients." (PMID 30159102, 2018). "In the past few years, an increasing number of publications have associated IL-34 with a bad prognosis in rheumatoid arthritis (RA) 111,112,113,114." (PMID 33408768, 2021). "Due to its osteoclastogenic effect, IL-34 is continuously being investigated as a potential diagnostic marker for inflammatory bone and joint diseases such as rheumatoid arthritis (RA)." (PMID 32801364, 2020). "Recently, IL-34 was found to be associated with chronic inflammation, such as in rheumatoid arthritis (RA)." (PMID 28036035, 2016). "Previous studies have reported increased IL-34 levels in plasma in PD and systemic inflammatory conditions, such as rheumatoid arthritis." (PMID 40389754, 2025). "IL-34 and CSF-1 levels are altered in several chronic inflammatory diseases, including periodontitis, rheumatoid arthritis and inflammatory bowel disease, making them interesting candidates as potential therapeutic targets or biomarkers of disease." (PMID 40389754, 2025). "These IL-34-induced divergent effects on the course of pathological inflammation are not seen exclusively in the gut, as similar findings were documented in rheumatoid arthritis (RA)." (PMID 39451216, 2024). "More specifically, IL-34 is overexpressed in the inflamed synovium of rheumatoid arthritis patients, where it appears to act synergistic with TNF and IL-1β, inducing osteoclastogenesis and contributing to tissue inflammation and bone erosion." (PMID 35347503, 2023). "Dysregulation of IL-34 is involved in many diseases, including inflammatory bowel disease, rheumatoid arthritis, chronic heart failure and ischemia/reperfusion injury-incited acute kidney injury." (PMID 35347503, 2023). "IL-34 plays a role in the induction and differentiation of osteoclasts and it is a proinflammatory factor leading to bone destruction in patients with rheumatoid arthritis." (PMID 37551285, 2022). "Like IL-32, IL-34 is also up-regulated in diseased tissues including for inflammatory bowel disease, rheumatoid arthritis, and ischemia/reperfusion injury driven acute kidney injury, however it is down-regulated in gastric cancer." (PMID 36438052, 2022). "IL-32 and IL-34 are key cytokines driving the development of chronic inflammatory conditions such as rheumatoid arthritis, systemic lupus erythematosus, as well as chronic liver diseases." (PMID 36438052, 2022).
rheumatoid arthritis (continued). "The level of IL-34 in the SF and serum in patients with rheumatoid arthritis, and after treatment, the levels of IL-34 in SF and serum decreased." (PMID 37551285, 2022). "Ding and colleagues showed that, in Chinese patients with rheumatoid arthritis, low serum level of IL-34 (≤194.12 pg/ml) at baseline was a good predictor of response at 3-month following anti-TNF-α treatment." (PMID 34535634, 2021). "Scholars from Dalian Medical University found that IL-34 increases the expression of IL-6 and then upregulates Th17 to participate in the course of rheumatoid arthritis." (PMID 34095310, 2021). "Serum IL-34 and CSF1 are linked to the disease activity in patients with rheumatoid arthritis and osteoporosis." (PMID 32801364, 2020). "The plasma concentration of IL-34 in synovial fluid and serum is low, but in rheumatoid arthritis, the content of IL-34 is dramatically increased, hence it's level is a useful biomarker for predicting the progression of rheumatoid arthritis." (PMID 33415105, 2020). "Macrophage growth factors are implicated in several inflammatory conditions including Sjögren’s syndrome where IL-34 expression is increased in the salivary glands, and in rheumatoid arthritis (RA) where IL-34 is increased in serum and synovial fluid." (PMID 27898738, 2016). "The involvement of IL-34 in RA (rheumatoid arthritis) and other inflammatory conditions has caught recent interest." (PMID 25896238, 2015). "This study was undertaken to address the expression of IL-34 in rheumatoid arthritis (RA) patients and to investigate its regulation and pathogenic role in RA." (PMID 22264405, 2012). "Moreover, studies have also shown that IL-34 promotes the expression of IL-17A, IL-6 and IL-1β in atherosclerosis, rheumatoid arthritis and inflammatory bowel diseases." (PMID 39883639, 2025). "IL-34 is an endogenous factor that repopulates hypermetabolic M34 macrophages and promotes cross-regulation with effector T cells to promote inflammatory bone resorption in rheumatoid arthritis." (PMID 40724937, 2025). "Rheumatoid arthritis (RA) is a chronic inflammatory disease characterized by proliferation and insufficient apoptosis of fibroblast-like synoviocytes (FLSs).The biology and functions of interleukin (IL)-34 are only beginning to be uncovered." (PMID 34385542, 2021). "The serum level of IL-34 is elevated in rheumatoid arthritis (RA) patients." (PMID 29472590, 2018). "Indeed, it has been demonstrated that IL-34 has involvement in cartilage and bone erosion by promoting osteoclastogenesis in rheumatoid arthritis." (PMID 26146640, 2015). "Interleukin-34 (IL-34) is a recently discovered cytokine functionally overlapping macrophage colony stimulating factor (M-CSF), a mediator of inflammation and osteoclastogenesis in bone-degenerative diseases such as rheumatoid arthritis." (PMID 24339952, 2013). "Serum levels of IL‐34 are significantly increased in patients with rheumatoid arthritis (RA) and correlate with disease severity." (PMID 32573824, 2020). "Recent study revealed that IL-34 plays important roles in the pathogenesis of chronic inflammations such as in rheumatoid arthritis (RA)." (PMID 28036035, 2016). "Although it has been shown that increasing IL-34 levels is associated with synovitis severity of rheumatoid arthritis patients, IL-34 expression could suppress joint inflammation as a negative feedback instead of promoting inflammation." (PMID 26146640, 2015). "IL-34 has been shown to be involved in the process of osteoclastogenesis and rheumatoid arthritis (RA)." (PMID 25395235, 2015). "A FPA008 trial in 12 rheumatoid arthritis patients and a phase 1 study of ARRY-382 in cancer patients have been reported as meeting abstracts and show that CSF1R inhibition leads to increased serum CSF1 and/or IL-34 levels and diminished NTX228,229." (PMID 32801364, 2020).
rheumatoid arthritis (continued). "More specifically, it has been demonstrated that the biological action of IL-34 involved in inflammation is mediated through pro-inflammatory cytokines including tumor necrosis factor-alpha (TNF-α) and IL-1β in fibroblast-like synoviocytes (FLS) isolated from rheumatoid arthritis (RA) patients." (PMID 32409720, 2020). "Serum concentrations of IL-34 in various inflammatory and autoimmune diseases including obesity, insulin resistance (IR), coronary artery diseases (CAD) and rheumatoid arthritis (RA), lupus nephritis are significantly elevated." (PMID 30478377, 2018). "Expression of IL-34 in obesity, inflammatory bowel disease (IBD), rheumatoid arthritis (RA), lupus nephritis and coronary artery diseases (CAD) are significantly elevated." (PMID 30478377, 2018). "Furthermore, it has been reported that TNF-α upregulates osteoclastogenic cytokine IL-34 production through the activation of NF-κB and JNK signaling in the synovial cells of rheumatoid arthritis (RA) patients." (PMID 33947456, 2021).
breast cancer (24 papers, 2013 to 2026). A primary or metastatic malignant neoplasm involving the breast. "With the exception of certain subtypes of breast cancer, an increase in IL-34 in the serum has been associated with poor prognosis." (PMID 33408768, 2021). "In mammary cancer and other tumors (i.e., teratoma, hepatocellular carcinoma), the pro-tumoral effect of IL-34 has been linked to the ability of the cytokine to promote the function of type 2 macrophages." (PMID 33298879, 2020). "We report that IL-34 expression is associated with differential outcome in intrinsic breast cancer subtypes." (PMID 29796177, 2018). "To explore their potential biological role, we studied the association between IL-34, CSF-1 and their receptors with immune cell infiltration based on the breast cancer dataset of The Cancer Genome Atlas (TCGA)." (PMID 29796177, 2018). "Initial evidence suggests the involvement of IL-34 in mammary cancer in which IL-34 levels have been associated with shorter survival and time to recurrence following cytotoxic therapies." (PMID 29423057, 2018). "In conclusion, our study shows that the mRNA expression pattern of IL-34 was distinct from CSF-1 and associated with a favorable prognosis dependent on the molecular breast cancer subtype." (PMID 29796177, 2018). "Here, we measured the levels of IL-34 in breast cancer patients using qRT-PCR and assessed the association of IL-34 expression with breast cancer outcome." (PMID 29796177, 2018). "We then investigated whether IL-34 expression differs between distinct molecular breast cancer subtypes and if IL-34 expression is associated with OS in these subtypes." (PMID 29796177, 2018). "The finding that high levels of IL-34 are associated with better prognosis in certain breast cancer subtypes is surprising, since the expression of CSF-1 and the common receptor CSF-1R has been linked to aggressive behavior and poor prognosis in breast cancer patients." (PMID 29796177, 2018). "Thus, IL-34 mRNA expression levels are associated with differential prognosis in PAM50 breast cancer subtypes in the TCGA dataset." (PMID 29796177, 2018). "Spatial transcriptomics on these brain metastases revealed that breast cancer cells produce interleukin-34 (IL34), which induces ARG1+ macrophages at the invading edge of metastases." (PMID 42166785, 2026). "Analysis of IL-34 RNA expression and breast cancer subtypes showed that high IL-34 expression correlated with a better prognosis in luminal and HER2 subtypes and a worse prognosis in the basal one." (PMID 35936748, 2022). "Although the binding of IL-34 to CSF1R modulates several cancer-driving signaling pathways, little is known about the role of IL-34/CSF1R signaling in breast cancer." (PMID 33800170, 2021). "Next, we examined the effects of IL-34 on MCF7 breast cancer cell growth using a BrdU incorporation assay and a soft agar assay." (PMID 33800170, 2021). "IL-34 can promote cancer in a variety of solid tumors such as gastric cancer, colorectal cancer, liver cancer, and breast cancer." (PMID 34336646, 2021). "Analysis of IL-34 RNA expression and breast cancer subtypes showed that high IL-34 expression correlated with a better prognosis in luminal and HER2 subtypes and worse prognosis in the basal one." (PMID 31968663, 2020). "In vitro experiments showed that IL-34 and M-CSF-1 differently modulate breast cancer cell migration, depending on the molecular subtype analyzed." (PMID 31968663, 2020). "Analysis of TCGA breast cancer RNA-seq data sets showed that IL-34 expression was lowest in luminal B subtype (p < 0.0001 vs. normal)." (PMID 29796177, 2018). "Our in vitro experiments provide evidence that IL-34 regulates cancer cell migration and mediates signaling in human breast cancer cells." (PMID 29796177, 2018). "To further elucidate the relationship between IL-34 and breast cancer, we used breast cancer data generated by The Cancer Genome Atlas (TCGA)." (PMID 29796177, 2018).
breast cancer (continued). "Together with our in vitro experiments these findings suggest that CSF-1R-independent actions of IL-34 via PTPRZ1 should be considered in evaluating IL-34 roles in breast cancer subtypes." (PMID 29796177, 2018). "We analyzed IL-34 mRNA expression in breast cancer cell lines and breast cancer patients and applied established computational approaches (CIBERSORT, ESTIMATE, TIMER, TCIA), to analyze gene expression data from The Cancer Genome Atlas (TCGA)." (PMID 29796177, 2018). "In vitro experiments in luminal and basal type breast cancer cells revealed that IL-34 and CSF-1 differentially regulate cancer cell migration dependent on the molecular subtype." (PMID 29796177, 2018). "Collectively, these results indicated that IL-34 and CSF-1 differentially activated signaling pathways in three breast cancer cell lines representing luminal, HER-2 and basal intrinsic subtypes." (PMID 29796177, 2018). "Together, these data indicate that breast cancer cells have a varying potential to respond to IL-34." (PMID 29796177, 2018). "Collectively, our data suggest that correlation of IL-34 gene expression with survival is dependent on the molecular breast cancer subtype." (PMID 29796177, 2018). "To analyze the expression of IL-34 by cancer cells, we examined IL-34 expression in 14 breast cancer cell lines and 4 normal breast epithelial cell lines." (PMID 29796177, 2018). "In vitro experiments showed that tyrosine phosphorylation of CSF-1R, ERK, and FAK and cell migration are differentially regulated by IL-34 and CSF-1 in breast cancer cell lines." (PMID 29796177, 2018). "Expression levels of IL-34 were comparable between metastases samples and healthy tissue although some breast cancer brain metastases display very high expression of this gene." (PMID 26098772, 2015). "Furthermore, JUN mediates the functions of some important cytokines in breast cancer, such as IL-34, IL-33, and IL-1β." (PMID 35127514, 2021). "However, the results were more contrasted in breast cancer in which IL-34 displayed different prognosis properties depending on the cancer subtype." (PMID 33408768, 2021). "In addition, our study demonstrates the regulatory role of PIN1 in breast cancer tumorigenesis induced by IL-34." (PMID 33800170, 2021). "Furthermore, to understand the role of PIN1 in the IL-34-induced MAPK pathway in breast cancer, we transfected the cells with mock and Xpress-PIN1 or siRNA-control and siRNA-PIN1, followed by treatment with or without IL-34 in MCF7 cells." (PMID 33800170, 2021). "The different behavior of IL-34 in breast cancer prognosis could be explained by the differential expression of IL-34 in basal cells between the luminal B and HER2 subtypes." (PMID 33408768, 2021). "It has also been demonstrated that IL-34 regulates the migration of breast cancer cells." (PMID 33800170, 2021). "In conclusion, this study documents a formerly unknown role of IL-34 in human breast cancer tumorigenesis and epithelial cell transformation through its interaction with CSF1R." (PMID 33800170, 2021). "Furthermore, the in vivo effects of IL-34 on tumor development were studied in a mouse model of 4T1 metastatic mouse breast carcinoma cells." (PMID 33800170, 2021). "IL‐34 has been shown to be over‐secreted in an in vitro study of breast cancer." (PMID 32573824, 2020). "However, while the role of CSF-1/CSF-1R has been extensively studied in breast cancer, the implication of IL-34 in breast cancer formation and progression is still poorly understood." (PMID 29796177, 2018). "Despite the known expression of CSF-1 and CSF-1R in human breast cancer and their clear therapeutic potential, the role of IL-34 remains unclear." (PMID 29796177, 2018). "To clarify the signaling basis by which IL-34 and M-CSF may differently regulate breast cancer cells, we investigated signaling events triggered by IL-34 and CSF-1." (PMID 29796177, 2018).